PTMAP9 (prothymosin alpha pseudogene 9)
Gene: Processed pseudogene on chromosome 12 (12,111,163 to 12,111,489, forward strand). Ensembl gene ENSG00000198134.
Diseases named in the same sentence as PTMAP9 in open-access papers:
PTMAP9 is named in the same sentence as 1 disease in open-access papers, as found by Europe PMC text mining. Sharing a sentence is not in itself a finding about the gene and the disease. The quoted sentences say what the papers report.
Hypertension (1 paper, 2025). The presence of chronic increased pressure in the systemic arterial system. "Among tissues linked to hypertension, PPP1R14D (Z = 3.12) and AMN (Z = 2.12) show maximal expression in kidney cortex, while PTMAP9 (Z = 1.16), RRAGA (Z = 1.37) and CREB1 (Z = 1.21) are most abundant in the aorta." (PMID 40909129, 2025).